CXCL1 (C-X-C motif chemokine ligand 1)
Diseases named in the same sentence as CXCL1 in open-access papers (continued):
Sharing a sentence is not in itself a finding about the gene and the disease.
tumor (continued). "CXCL1, for example, is a chemokine that attracts neutrophils and other immune effector cells to the tumor site, amplifying immune cell-mediated cytotoxicity." (PMID 39372411, 2024). "FC analysis of the tumor tissues revealed that knockdown of CXCL1 combined with PD-1 antibody treatment markedly augmented the amount of CD8+ T cells and IFNγ+ cells and reduced the abundance of MDSCs." (PMID 38510750, 2024). "The authors suggested an interesting mechanism that CXCL1-mediated neutrophil recruitment is the primary signal necessary to rewire the TME in favor of tumor growth." (PMID 38786066, 2024). "We further showed that inhibition of SQLE led to a squalene-dependent reduction in the recruitment of immunosuppressive cells to the tumor microenvironment involving the CXCL1-mediated pathway." (PMID 39763673, 2024). "IL-17A can selectively elevate the expression of chemokines with angiogenic properties by epithelial cells as well as tumor cells, such as CXCL1, CXCL5, CXCL6, and CXCL8." (PMID 38515019, 2024). "Since the cytokines (Cxcl1 and Csf3) involved in immune cell recruitment and survival and Cd84 are elevated at day 7 in tumor-bearing mice, we tested if Ly6G+ mononuclear cells are present in MHV68-infected mice and are also a source of IL-6." (PMID 39338937, 2024). "Given its involvement in multiple aspects of tumor progression and metastasis, CXCL1 has emerged as a potential therapeutic target in cancer treatment." (PMID 39057432, 2024). "This gap is addressed by a series of our reviews on CXCL1 that aims at making it easier to grasp the significance of CXCL1 in tumor processes." (PMID 38673949, 2024). "The decrease in CXCL1 has less ability to attract immunosuppressive cells such as MDSCs and TAMs, and thus maintaining an anti-tumor immune microenvironment." (PMID 39763673, 2024). "IL-17A produced by neutrophils exacerbates tumor growth by inducing CXC chemokines (CXCL1, CXCL2, CXCL3, CXCL5, CXCL8, and CXCL11) in gastric cancer cells to recruit neutrophils to the invasive edge." (PMID 39906741, 2024). "The recruitment of tumor-associated macrophages (TAMs) to tumor sites is mediated by chemokines such as CCL2, CCL5, CCL7, CXCL1, CXCL2, and CXCL4, which promote tumor survival." (PMID 39769501, 2024). "Our results showed that 4T1/WT tumors contained higher levels of CXCR2 ligands, such as CXCL1/2/3, known to attract MDSCs into the tumor, thereby enhancing cancer cell survival." (PMID 38612760, 2024). "Treatment of tumor stromal organoids in culture with docetaxel induces cytokine secretion (Csf3, Csf2, Il-6, Cxcl1, Cxcl2, and Tnfα) into the cell culture media while reducing levels of Vegf." (PMID 39338937, 2024). "The expression of CXCL1 is intricately regulated by miR-146a, influencing neutrophil recruitment and subsequently promoting tumor growth." (PMID 38474175, 2024). "CXCL1, often overexpressed in tumors, functions by binding to its receptor on the surface of neutrophils, guiding them toward the tumor site." (PMID 38360737, 2024). "In contrast, iCAFs are located further away from tumor cells and lack α-SMA and express high levels of the chemokines interleukin 6 (IL6) and C-X-C motif chemokine ligand 1 (CXCL1), which support tumor progression." (PMID 39273316, 2024). "The neutrophil-produced tumor necrosis factor (TNF) induces feed-forward CXCL1 overproduction in both tumor cells and CAFs, leading to T-cell suppression." (PMID 38339310, 2024). "Recently, it has been shown that following the ligation of these chemokines, such as CXCL1 to CXCR2, tumor-associated immune cells can recruit into the tumor milieu to suppress anti-tumor immune responses and also activate the angiogenic processes." (PMID 38515019, 2024). "Inhibiting CXCL1 signaling can therefore impede tumor growth and reduce the tumor’s ability to access essential nutrients." (PMID 39057432, 2024).
tumor (continued). "Specifically, tumor-derived SPP1 acted on lung epithelial cells via the CD44/CXCL1 axis to increase local neutrophil infiltration." (PMID 39529085, 2024). "Using snRNA-seq and imaging mass cytometry, CD8+ T cells were spatially excluded from the contiguous PanCK+ CXCL1+ tumor cell and tumor-infiltrated neutrophil (CXCR2+ CD11b+ CD15+) communities." (PMID 38786066, 2024). "The metabolic removal of squalene by SQLE causes the activation of NF-κB pathway and promote the expression of CXCL1, leading to elevated infiltration of immunosuppressive cells in the tumor tissues to facilitate tumor growth." (PMID 39763673, 2024). "TAMs and TANs can be recruited into the tumor microenvironment by chemokines produced by cancer cells, such as the chemokines signaling axis CXCL1, CXCL2, CXCL5, CXCL8–CXCR2, and CXCR1." (PMID 39769501, 2024). "The results revealed that BHS, when combined with paclitaxel, synergistically suppressed neoangiogenesis in both tumour tissues and lung metastatic foci, which was also closely correlated with EV‐Apo/CXCL1." (PMID 39051750, 2024). "Similar to the s.c. flank model, orthotopic MOC1 tumors exhibited high levels of CXCL1 expression in tumor cells and CXCR2 expression in CD45+ immune cells when evaluated by RNA in situ hybridization." (PMID 39639338, 2024). "These TAMs subsequently augment tumor cell mobility and self-renewal capacity through the secretion of CXCL1." (PMID 39286635, 2024). "Recent studies identified tumor necrosis factor (TNF) derived from TANs as central immune regulators that contribute to feed-forward CXCL1 overproduction by tumor cells and fibroblasts via transmembrane TNF-TNFR2 interactions." (PMID 38167055, 2024). "The findings suggested that BHS inhibited the autophagic activity induced by paclitaxel in tumour tissues and lung metastases, and EV‐Apo/CXCL1 signalling also significantly contributed to this process." (PMID 39051750, 2024). "We found that the addition of MSCs to a tumor cell culture induced the expression of chemokines CXCL1, CXCL5, and CXCL13." (PMID 38182756, 2024). "To elucidate the factors governing G-MDSC recruitment in CRNDE-induced HCC, we examined putative G-MDSC-recruiting chemokines, indicating that the expression of Cxcl3, Cxcl1, Cxcl5, and Ccl2 was significantly increased in upregulated Crnde tumor cells." (PMID 38169579, 2024). "F. nucleatum was thoroughly correlated with increased tumor invasion and lymph node or distant metastases, promoting metastasis by regulating signaling molecules, including IL-8, C-X-C motif chemokine ligand 1 (CXCL1), and keratin 7 (KRT7)." (PMID 39201711, 2024). "In contrast, tumor-associated macrophages (TAMs) recruited by CCL221 and MDSCs recruited by CXCL1/CXCL322 have been shown to be closely related to the immunosuppressive TME." (PMID 38169579, 2024). "Although we predict that CBX2-mediated regulation of TAM differentiation and activity is highly complex, our findings suggest a unique CBX2/CXCL1 or CBX2/CXCL8 axis in tumor cells that aid in remodeling the HGSC TIME." (PMID 38984891, 2024). "The binding of CXCR2 to its ligands, including CXCL1 and IL-8, triggers intracellular-signaling pathways that guide TANs toward the tumor site." (PMID 38360737, 2024). "Neutrophil-derived TNF regulates immunologic rewiring, CXCL1 overproduction from tumor cells, and T cell dysfunction." (PMID 38474175, 2024). "EREG (−/−) mice have significantly lower levels of inflammation (macrophages, polynucleated leukocytes, and CXCL1) compared to wildtype mice, as well as significantly reduced tumor incidence." (PMID 38334792, 2024). "We found that the Mg‐CaCO3 exhibited rapid and stable hydrogen release capability in the weak acid TME, reduced pro‐tumor and immune suppressive factor generation of CAFs including Cxcl1 and Cxcl12, and augmented anti‐tumor immune activities of CD4+ T cells." (PMID 38757665, 2024).
tumor (continued). "Previous data suggest that once pIRF3 enters the nucleus, it activates the type I IFN response, consequently stimulating the secretion of chemokines, Chemokine (C-C motif) ligand 5 (CCL5), and C-X-C Motif Chemokine Ligand 1 (CXCL10) in tumor cells." (PMID 38169513, 2024). "Tumor-derived CXCL1 plays an important role in migration and invasion by influencing the polarization of macrophages." (PMID 38713320, 2024). "Hepatic infiltration and activation of MDSCs can be regulated by inflammatory chemokines (e.g., CXCL1 and CCL2) and cytokines (e.g., IL-6), tumor-associated fibroblasts, epigenetic factors, and gut microbiota during liver pathogenesis." (PMID 38397901, 2024). "For instance, IL-17A can influence Treg function by affecting MDSCs and recruiting MDSCs to tumor sites via the secretion of chemokines CXCL1/2." (PMID 39906741, 2024). "Following their development in the bone marrow, neutrophils undergo mobilization into the bloodstream and are subsequently recruited to tumor sites, facilitated by factors such as CXCL1." (PMID 38474175, 2024). "CXCL1, a chemokine expressed in tumor cells or stromal cells, was reported to mediate angiogenesis and promote tumor progression." (PMID 38167009, 2024). "CXCL1 is also important in tumor nest formation in cSCC —small clusters of tumor cells in the immediate vicinity of a tumor that are indicative of tumor cell migration and tumor growth." (PMID 38673949, 2024). "The interaction between CXCL1 and the abundance of CXCR2 on neutrophils leads to the accumulation of tumor-associated neutrophils (TANs) at these sites." (PMID 38474175, 2024). "In this process, insulin-like growth factor-I (IGF-I) causes self-renewal of NSCLC cancer stem cells, followed by an increase in CXCL1 and placental growth factor (PlGF) expression in these cells, leading to angiogenesis and recurrence of the tumor." (PMID 38673949, 2024). "After chemotherapy, neutrophils are recruited via tumor cell-secreted CXCL1 and CXCL2 signaling to the liver, where chemotherapy increases the expression of growth arrest specific 6 (Gas6) in circulating neutrophils." (PMID 38982491, 2024). "CXCL1 promotes tumor progression by enhancing cell growth, motility, invasion, angiogenesis, and metastasis, making it a critical factor in the aggressive behavior of cancer cells across different types of cancer." (PMID 39408697, 2024). "Agreeing with this study, we also see high expression of CXCL1 in tumor cells, and high expression of the corresponding receptor CXCR1 in neutrophils, suggesting a mechanism by which neutrophils are recruited into the interior of the tumor." (PMID 38712065, 2024). "KLK6 is a secreted serine protease, which promotes the production of TNF-α by macrophages through PAR1 in the TME to stimulate the production of CXCL1 in tumor cells, thereby promoting tumor growth and metastasis." (PMID 38363409, 2024). "Previously, the CXCL1/CXCR2 axis was found to play a key role in promoting MDSCs chemotaxis in the tumor environment." (PMID 38510750, 2024). "With radiation therapy, there is an increase in CXCL1 expression, which increases the resistance of the tumor to treatment." (PMID 38673949, 2024). "For this reason, tumor mechanisms are being studied to develop new therapeutic approaches in this disease; one possible target is CXCL1." (PMID 38673949, 2024). "Tumor size was positively correlated with levels of CXCL1 (r = 0.17, P = 0.048), CXCL8 (r = 0.18, P = 0.037), and IL6 (r = 0.27, P = 0.009)." (PMID 38965454, 2024). "Through Akt–NF-κB–MMP-9/14 signalling, LAMC1 promoted the multiplication, infiltration of tumour cells, increased CXCL1 production and enhanced the development of iCAFs, resulting in enhanced tumour growth both in vitro and in vivo." (PMID 37927475, 2023). "This CXCL1 secretion leads to a decrease in enzyme activity, increased DNA damage repair, and, ultimately, tumor radioresistance." (PMID 37468464, 2023).
tumor (continued). "Pro-tumor N2 neutrophils are known to influence cancer progression by the secretion of C-X-C motif chemokine ligand 1 (CXCL1), matrix metallopeptidase 9 (MMP-9), VEGF, and TNF-alpha, as well as ROS and NO." (PMID 37427115, 2023). "CXCL1 expression in tumor stroma is positively correlated with perineural invasion, N stage, and T stage." (PMID 37408240, 2023). "CXCL1 can recruit c-Kit+Ly6a/Sca1+ hematopoietic stem/progenitor cells into the tumor niche, as demonstrated by experiments in mice." (PMID 37108425, 2023). "We further proved that CXCL1/IL8 directed the recruitment of neutrophils and likely supported tumor‐associated macrophage (TAM) filtration." (PMID 37078828, 2023). "The high inflammation level in the TME promotes tumour progression, partly through the CXCL1 signalling pathway." (PMID 37037815, 2023). "CXCR2-positive MDSCs are recruited into the tumor microenvironment via chemokines CXCL1 and CXCL2 mainly expressed in tumor colonic epithelial cells, which is critical for colitis-associated tumor formation and progression." (PMID 37124519, 2023). "The high importance of CXCL1 in tumor processes is reflected in the impact of this chemokine on patient prognosis." (PMID 37408240, 2023). "The results revealed that Cxcl1 silencing contributed to reduced tumor growth and improved survival." (PMID 37455286, 2023). "Intratumoral knockdown (KD) of Serpinb3a resulted in tumor growth inhibition and reduced CXCL1 and S100A8/A expression and MDSC and M2 macrophage infiltration." (PMID 37279067, 2023). "OV-mediated ICD triggers the release of IL-6, IL-8, IFN-β, IP-10 (CXCL10), MCP-1 (CCL2) and KC (CXCL1) from cancer cells to recruit different immune cells and initiate an anti-tumor response." (PMID 36831636, 2023). "By increasing the expression of CXCR2, for example through transduction, such cells can specifically migrate to the tumor site with high levels of CXCL1 and other CXCR2 ligands." (PMID 37108425, 2023). "CXCL1 promotes the proliferation and migration of colon cancer cells and has a facilitating effect on tumor angiogenesis." (PMID 37371856, 2023). "In mouse models of different tumour entities, CXCL1, which seems to be exclusively produced by iCAFs, promoted the infiltration of polymorphonuclear (PMN)-MDSCs into the TME and drove tumour progression." (PMID 36480035, 2023). "As CXCL1 and LAMC2 are associated with recruitment of neutrophils and macrophages into tumor tissue, these results demonstrate the significant role of immune cell population in LUAD growth." (PMID 36973297, 2023). "In cancer cells, adiponectin has been shown to induce CXCL1 secretion and thereby promote tumour angiogenesis." (PMID 37175937, 2023). "CXCL1 is a chemotactic factor that recruits MDSCs into the tumor microenvironment by binding to its receptor CXCR2." (PMID 37865804, 2023). "CXCL1 has a role in angiogenesis and arteriogenesis and thus has been shown to act in the process of tumour progression." (PMID 38022682, 2023). "This is the major receptor involved in MDSC infiltration to the tumor site after binding with its ligand, CXCL1 or CXCL2, produced by the tumor cells." (PMID 37513979, 2023). "Signaling through CXCL1 and CXCL2 is mainly responsible for recruitment of immune suppressive tumor associated neutrophils as well as PMN-MDSC." (PMID 37964379, 2023). "Based on previously reported studies, it has been documented that IL1B, CXCL1, CDK6, and IGFBP3 were closely associated with tumor radiosensitivity." (PMID 37468464, 2023). "There is a positive correlation of CXCL1 expression in the tumor with TNM classification stages, macrovascular invasion, microvascular invasion, and distant metastasis." (PMID 37408240, 2023). "Next, we demonstrated in mice that transfusions of Hepa1–6 cells stimulated with CXCL1 recombinant protein produced larger tumours in the liver than unstimulated cells." (PMID 37037815, 2023).
tumor (continued). "CXCL1 expression is also higher in ESCC stages II–IV than in stage I, showing that the expression of CXCL1 increases with tumor growth and development." (PMID 37408240, 2023). "The level of CXCL1 expression in the tumor is negatively correlated with distant metastasis, and higher CXCL1 expression in the tumor is a better or worse prognosis for patients." (PMID 37408240, 2023). "Consistently, we further observed ETV4 mRNA expression levels positively correlated with CXCL1 or CXCL8 mRNA expression levels in the tumor tissues." (PMID 36670069, 2023). "In MC-38 tumor grafts, using the same experimental set-up as in RM-9, radiation increased mRNA levels of CXCL1, CXCL2, CXCL3, and CXCL5 at 24 h post-treatment and protein levels of CXCL5 at 24 h and 48 h post-treatment." (PMID 38067390, 2023). "Increased levels of tumor-infiltrating monocytes and macrophages in TCGA STAD samples highly expressing CXCL1 are suggestive of enhancing tumor invasion and migration." (PMID 36614235, 2023). "IL-8 and CXCL-1, whose secretions are increased in obese ASCs, have also been shown to contribute to the recruitment of ASCs into the tumor site." (PMID 36766689, 2023). "TRIM28 overexpression in CMT-167 tumors led to an upregulation of CXCL1 levels in tumor tissue, tumor lysates, and serum." (PMID 37865804, 2023). "For instance, HFD-induced obese mice showed increases in VEGF, IL-6, chemokine ligand 2 (CCL2), and C-X-C motif chemokine ligand 1/2/13 (CXCL1/2/13), which promote angiogenesis and the infiltration of immune cells that favor tumor development and metastasis." (PMID 36670988, 2023). "Elevated levels of CXCL1 in tumors have been shown to play a fundamental role in tumor malignancy and metastasis across various cancer types." (PMID 37865804, 2023). "They found that reprogramming of PMN-MDSCs generated in Cxcl1-silenced tumor-bearing hosts disrupted their migratory potential and reduced immunosuppressive markers." (PMID 37455286, 2023). "CXCL1 functions as a chemokine that attracts MDSCs to the tumor microenvironment by signaling via the G protein-coupled chemokine receptor CXCR2." (PMID 37865804, 2023). "After the occurrence of metabolic disorders, insulin activates the paracrine connection between tumor cells on the CXCL1/CXCR12 axis and CAFs, triggering the movement phenotype of tumor cells." (PMID 37978384, 2023). "CXCL1 expression levels in tumour samples from HCC patients were analysed through the GEPIA database." (PMID 37037815, 2023). "Further, the prognosis is worse for rectal adenocarcinoma patients with a high CXCL1 expression in the tumor." (PMID 37408240, 2023). "We present the molecular contribution of CXCL1 to chemoresistance and radioresistance in selected tumors and its influence on the proliferation, migration, and invasion of tumor cells." (PMID 37108425, 2023). "The pre-inoculation of CXLC-1 loaded PLGA hydrogel near the tumor site created an artificial tumor microenvironment by the sustained release of CXCL-1 that attracted paclitaxel-nanoparticle bearing neutrophils to the tumor site in a “trojan-horse” manner." (PMID 36839937, 2023). "In mouse models of TNBC, tumor-derived EVs containing the pluripotent factor Lin28B were found to upregulate the expression of CXCLs (CXCL1, CXCL2, CXCL3, and CXCL5) in the lung tissue, resulting in neutrophil infiltration." (PMID 37496019, 2023). "Of these tumor size-associated cytokines, seven (TNF-β, MCP-3/CCL7, Fractalkine/CX3CL1, GRO/CXCL1, sCD40L, TGF-α, and MDC/ADAM11) were among those newly investigated as part of a bead array-based vitreous cytokine analysis of UM." (PMID 37509362, 2023). "To corroborate these findings in vivo, we examined CXCL1 levels in tumor tissue, tumor lysates, and serum from a syngeneic CMT-167 tumor model." (PMID 37865804, 2023).